STC1 (stanniocalcin 1)
Diseases named in the same sentence as STC1 in open-access papers (continued):
Sharing a sentence is not in itself a finding about the gene and the disease.
tumor (continued). "Expression of tumor stanniocalcin 1 (STC1) is reported to be related to immunotherapy efficacy and is negatively linked with patient survival in LUAD by tumor immune evasion and immunotherapy resistance." (PMID 35620481, 2022). "Molecular mechanism investigation revealed that circPOSTN exerted its tumor-promoting effects by acting as a ceRNA to sponge miR-219a-2-3p and therefore upregulating STC1 and VEGFA expressions." (PMID 35927233, 2022). "IGF1 was also expressed in the CAFs while IGFR1 was predominantly expressed in the tumor cells: STC1, STC2 and IGFBP4 were expressed in both tumor cells and CAFs." (PMID 35205651, 2022). "Since the most common subtype of OC is epithelial OC (EOC), we indicated that STC1 was highly expressed in OC tissues, which implied that STC1 was highly expressed in OC tumor cells, and the high expression of STC1 was related to metastasis in OC tissues." (PMID 35392966, 2022). "After that, we conducted an IHC assay of three types of tissues from TMAs and determined that STC1 expression was higher in tumor and peritoneal metastasis tissues than in para-carcinoma tissues, which verified the results of single-cell sequencing." (PMID 35392966, 2022). "Risk factors, like STC1, COL5A2, COL3A1, and BGN, were significantly correlated with poor OS, while BMPR2 and PGLYRP1 were only found to be protective factors in 2 of 33 tumor types." (PMID 36479101, 2022). "Mechanically, circPOSTN exerted its tumor-promoting effect by acting as a ceRNA to inhibit the miR-219a-2-3p/STC1 axis, upregulating the expression of oncogene STC1, and therefore facilitated VEGFA secretion." (PMID 35927233, 2022). "In murine tumor models, a gain of STC1 favors tumor progression and allows tumor resistance to checkpoint blockade." (PMID 35620481, 2022). "Research on STC1 is still attractive because STC1 can be easily detected in the blood and is potentially a predictive marker for tumor diagnosis and treatment." (PMID 34722511, 2021). "Using HCC cell-line analysis (Hep3B and MHCC97L), we also showed the inhibitory actions of STC1 on the growth of tumor spheroids in culture." (PMID 33156861, 2020). "Human stanniocalcin-1 (STC1) is a glycoprotein known to participate in inflammation and tumor progression." (PMID 33156861, 2020). "More extensive sample size studies with additional mechanistic data on tumor microenvironment are yet required to reveal STC1 functions in carcinogenesis." (PMID 33156861, 2020). "Our previous study showed that STC1 was upregulated in tumor tissues from the analysis of clinical data of 216 HCC patients." (PMID 33156861, 2020). "Our data support further investigations on the relationship between tumor STC1 level and macrophage infiltration." (PMID 33156861, 2020). "Increased peri-tumor distribution of F4/80+ cells in the Stc1−/− SPK lung was confirmed by immunohistochemistry." (PMID 32579928, 2020). "Previous studies have shown that STC1 is regulated by HIF-1 to promote tumor proliferation and metastasis." (PMID 33396393, 2020). "Our previous studies demonstrated that the inoculation of STC1-overexpressing MHCC97L cells in a nude mice xenograft model exhibited a reduction in tumor mass and volume." (PMID 33156861, 2020). "Among them, more research has been conducted on the anti-cisplatin effect of GAST, and GNRH1 and STC1 can activate the c-Jun N-terminal kinase (JNK) pathway to facilitate tumor development." (PMID 33330624, 2020). "STC1 also participates in EMT process to reshape the tumour microenvironment, promote the initiation of malignant phenotypes." (PMID 32468698, 2020). "Changes in the quantity of infiltrating TAM in STC1-overexpressing HCC derived tumor mass from nude mice were studied." (PMID 33156861, 2020). "Hydrocortisone and dexamethasone down‐regulate the STC1 expression level dramatically in several kinds of mouse and human tumour cell lines, and this effect is antagonized by activation of the cAMP signalling pathway." (PMID 32468698, 2020).
tumor (continued). "It has been well demonstrated that STC1 enhances tolerance to hypoxia in tumour cells and thus has an anti‐apoptosis effect on tumour cells." (PMID 32468698, 2020). "Since tumor progression is strongly influenced by the infiltrating immune cells, in the present study, the effects of tumor cell-derived STC1 on macrophages' differentiation and function were investigated." (PMID 33156861, 2020). "They found that tumours with higher expression levels of STC1 were significantly smaller than those with lower levels of expression (P = .008)." (PMID 32468698, 2020). "Stanniocalcin-1 (STC1) is a secreted glycoprotein, and its high expression levels were associated with tumor growth and metastasis in BC." (PMID 33489894, 2020). "The presence of STC-1 in tumor stroma is both necessary and sufficient for the inhibition of apoptosis in tumor cells." (PMID 31857958, 2019). "Both BNIP3 and STC1 are hypoxia-responsive genes, and their overexpression actuates tumor progression." (PMID 31212896, 2019). "In vivo, sevoflurane significantly inhibited the tumor growth, which was be reversed by STC1 overexpression." (PMID 31889892, 2019). "Further, we observed that the inhibition of sevoflurane in tumor growth was reserved by up-regulation of STC1." (PMID 31889892, 2019). "In summary, the present study showed the smaller tumor xenografts in nude mice and cell size derived from STC1-overexpressed metastatic human HCC-97L cells." (PMID 29467934, 2018). "Our previous study showed that STC1 was upregulated in the tumor tissues from the analysis of clinical data of 216 HCC patients." (PMID 29467934, 2018). "Using HCC cell-line analysis, we showed the inhibitory actions of STC1 on the pro-migratory effects of IL-6/IL-8, the growth of tumor spheroids in culture and the development of tumor mass in nude mice model." (PMID 29467934, 2018). "The involvement of STC1 in the processes of tumor growth, epithelial-mesenchymal transition (EMT) and apoptosis in various types of cancer were suggested." (PMID 29467934, 2018). "With the benefit of hindsight, in this study lentiviral-based overexpression approach was applied to monitor tumor growth in nude mice xenograft and to characterize in vitro functional implications of STC1." (PMID 29467934, 2018). "Considerable numbers of studies have also shown differential expressions of STC1 in paired human tumor and normal tissues." (PMID 29467934, 2018). "Consistent with the microarray data, the expression levels of STC1 in tumor tissues was greater than the corresponding normal tissues (2.89-foldincrease, p<0.05)." (PMID 26469082, 2015). "Expression of STC1 was determined in tumor-normal tissue paired samples using both microarray and qPCR." (PMID 26469082, 2015). "Accompanied with clinical analysis and nude mice studies, experimental investigations using human cancer cell lines identified various transcriptional factors that regulated STC1 expression in the process of tumor progression." (PMID 26469082, 2015). "We found that STC1 was upregulated in the tumor tissues and its expression levels was positively correlated with the levels of interleukin (IL)-6 and IL-8." (PMID 26469082, 2015). "STC1 mRNA and protein expression were significantly up-regulated in tumors when compared with non-tumor tissues, with the greatest increase in expression observed in metastatic tissues." (PMID 25740019, 2015). "In this work, we found that both STC1 mRNA and protein levels were up-regulated in ccRCC tissues when compared to their matched adjacent non-tumor counterparts." (PMID 25740019, 2015). "The microarray data showed that the expression of STC1 mRNA was increased by 1.49-fold in tumor tissues (mean 7.023) as compared with their normal counterparts (mean 4.728) (p<0.0001)." (PMID 26469082, 2015). "Intriguingly tumors with greater expression levels of STC1 (tumor/normal ≥ 2) were significantly smaller than the lower level (tumor/normal<2) samples (p = 0.008)." (PMID 26469082, 2015).
tumor (continued). "With respect to tumor size analysis using the clinical data, the cohort of STC1-High showed smaller size as compared to the STC1-low group, but this was found only in large tumors (>6.3cm in diameter)." (PMID 26469082, 2015). "In the present study, STC1 was found to be highly expressed in tumor tissues versus the adjacent normal counterpart, collected from the HCC cases." (PMID 26469082, 2015). "Taken together, our data indicate that STC1 drives tumor cell growth and proliferation, and is consistent with the tumor growth, and ultimately the metastasis observed for early stage ccRCC." (PMID 25740019, 2015). "The inhibitory effect of STC1 on tumor growth was confirmed in vivo using the stable STC1-overexpressing 97L cells on a mouse xenograft model." (PMID 26469082, 2015). "In our study, we identified a positive correlation between STC1 expression and average tumor diameter." (PMID 25740019, 2015). "We found that IL12 (isoforms A and B) and NLRP3 were upregulated in 97L/STC1-derived tumor xenografts." (PMID 26469082, 2015). "Experimental studies using ovarian, gastric, and colorectal tumor cells in nude mice supported the pro-oncogenic role of STC1." (PMID 26469082, 2015). "Considering the important roles of these markers, the effect of STC1 on these EMT markers has suggested its possible role in tumor progression." (PMID 25740019, 2015). "Anti-apoptotic effects have been reported for STC1 in some types of cancer, whereas pro-apoptotic effects have been observed in other tumor types." (PMID 24743310, 2014). "Our results showed that circulating STC1 or STC2 mRNA levels were significantly correlated with one or more features indicative of worse tumor biology." (PMID 24743310, 2014). "Some study indicated that STC1 expression was involved in the formation of tumor vasculature, and STC1 can induce adaptive responsive to hypoxia by HIF regulation in human cancer cells." (PMID 23382863, 2013). "Collectively, these data evidenced that down regulation of STC1 promoted in vivo xenograft tumor development." (PMID 23382863, 2013). "From above these results, we put forward the model for STC1-mediated inhibiting of tumor progression: After activation of the NF-κB p65, STC1 expression increased." (PMID 23382863, 2013). "But the relationship between the differentially expression of STC1 in tumor compared to normal tissue and its biological function needs further investigation." (PMID 23382863, 2013). "The STC1-positive cells were localized in various parts of the tumor including tumor surface, central zone, and deepest areas of the esophageal wall." (PMID 22200953, 2012). "In concordance with previous studies, we found that the level of STC-1 protein expression in ESCC was much higher than that in matched normal tissues, which further confirmed STC-1 as a promising tumor marker for ESCC." (PMID 22537917, 2012). "There were 71 cases (83.5%) showed a higher level of STC-1 protein expression in tumor tissues than in adjacent normal tissues (P < 0.001)." (PMID 22537917, 2012). "Twelve cases out of 15 showed higher expression of STC1 mRNA in the tumor tissue compared with normal counterparts." (PMID 22200953, 2012). "In total, there were 71 cases (83.5%) showed a higher level of STC-1 protein expression in tumor tissues than in normal tissues, and the average immunostaining scores in tumor tissues were 3.08 ± 1.81 while in normal tissues was 1.05 ± 1.08 (P < 0.001)." (PMID 22537917, 2012). "BGC/STC cells (high-expression of STC-1) and BGC/shSTC cells (low- expression of STC-1) were constructed to investigate the effect of STC-1 on the xenograft tumor growth and angiogenesis in vitro and in vivo." (PMID 21672207, 2011). "Besides, the expression of STC1 was also closely related to the tumor recurrence, and patients with high STC1 had a higher recurrence rate." (PMID 41020346, 2025). "STC1 has been shown to promote tumor cell viability and proliferation." (PMID 41342328, 2025).
tumor (continued). "With the further studies on the crosstalk between STC1 and TAMs in the TME, may have the potential to makes STC1 to become a novel biomarker, which can improve the accuracy of early diagnosis of tumors and determine tumor metastasis." (PMID 39654892, 2024). "In 2021, STC1 was reported to be involved in tumor immunity as a phagocytic checkpoint." (PMID 39654892, 2024). "Moreover, STC1 expressed in tumour cells promotes immune escape and resistance to immunotherapy by inhibiting APC phagocytosis." (PMID 38556542, 2024). "Finally, we obtained eight different cancer-related GEO datasets from the GEO database to confirm the difference in STC1 levels between normal and tumor samples." (PMID 39201771, 2024). "Strategies targeting STC-1 may help inhibit tumor growth and metastasis and improve chemotherapy efficacy." (PMID 39071498, 2024). "In addition, clarifying the mechanism and causes of differential expression of STC1 will help us understand the role and value of STC1 in tumor immunity." (PMID 39654892, 2024). "In addition, we proposed the future development directions and prospects for immunotherapy, hoping to provide references for the research of STC1 in tumor immunotherapy." (PMID 39654892, 2024). "Targeting STC1 can improve the efficacy of tumor immunotherapy." (PMID 39012409, 2024). "Previous studies reported that stanniocalcin-1 (SCT1) acted as a tumor growth factor to promote tumor proliferation, and that overexpression of SCT1 can promote tumor proliferation and subcutaneous tumor formation in mice, whereas inhibition of SCT1 reduced the tumor cell proliferation." (PMID 38215156, 2024). "This suggests that STC1 may influence the tumor immune response by modulating the activation, migration, or functional dynamics of these immune cell populations." (PMID 39201771, 2024). "STC1 has also been implicated in various cancer-related signaling pathways, including NF-kB, ERK1/2, JNK, and epithelial–mesenchymal transition (EMT), contributing to tumor initiation, invasion, metastasis, inflammation, and therapeutic resistance." (PMID 39186548, 2024). "Moreover, multiple researches have demonstrated that STC1 serves as a regulator of tumor immunity affecting differentiation, activation, inflammatory response, and antigen presentation of macrophages." (PMID 39654892, 2024). "In non-tumor diseases, STC1 affects the function of immune cells." (PMID 39201771, 2024). "In addition to this, STC1 promotes tumor neo-angiogenesis, which is the formation of new blood vessels inside a tumor." (PMID 39201771, 2024). "In our previous study with a tissue microarray cohort of hysterectomy specimens from 832 EnCa cases, 99.15% of the cases showed positive STC1 staining primarily in the endometrial epithelium, highlighting potential tumor microenvironment modulation via the EMT process." (PMID 39186548, 2024). "Comprehensive exploration of the function of STC1 on tumor immune cells and the immune microenvironment will facilitate the targeted therapy of STC1 and may improve the efficacy of immunotherapy." (PMID 37004088, 2023). "STC1 expression was found to be correlated with clinical T, metastasis, and tumor stage." (PMID 37543714, 2023). "Next, we inquired into the potential mechanism of STC1-induced promotion of tumor metastasis." (PMID 37400459, 2023). "One recent study showed that STC1 could inhibit the phagocytosis of antigen-presenting cells (APCs), leading to tumor immune escape and immunotherapy resistance." (PMID 37004088, 2023). "S100A4 mediates the functions of STC1 on tumor cells and the metastatic microenvironment." (PMID 37400459, 2023). "By analyzing the relationship between STC‐1 expression and clinicopathological features in each patient, we found that the expression of STC‐1 was closely associated with tumor grade, AJCC stage, T stage, N stage, M stage, breast subtype, ER status, PR status, and HER‐2 status." (PMID 36336967, 2023).
tumor (continued). "Under hypoxia conditions, STC1 could be modulated by Hypoxia-inducible factor-1 (HIF-1) to facilitate the reprogramming of tumor metabolism from oxidative to glycolytic metabolism." (PMID 36779699, 2023). "Previous researches have recognized the involvement of STC1 in tumor progression." (PMID 37400459, 2023). "STC‐1 has been reported to contribute to cancer progression by inhibiting apoptosis; promoting the vitality, proliferation, and invasiveness of cancer cells; and promoting tumor chemical resistance." (PMID 36336967, 2023). "MiR-20a-5p by targeting FGL2 and miR-139-5p by targeting STC1 could have an impact on tumor microenvironment by interacting with tumor-related inflammation and infiltration of macrophages and CD4+T cells." (PMID 38036953, 2023). "Importantly, tumor tissues with high A20 expression were also observed with high STC1 expression, and vice versa." (PMID 37607946, 2023). "In contrast, the effect of tumor cell-derived STC1 on stromal cells has been rarely reported." (PMID 37400459, 2023). "However, few studies have reported the role of tumor-derived secretory STC1 in tumor organ metastasis." (PMID 37400459, 2023). "The GSEA revealed that the genes correlated with PLCB1, including HEY1, EZH2, VEGFA, E2F3, and STC1, were enriched in angiogenesis, suggesting that the increased expression of PLCB1 might be associated with HCC recurrence via tumor-associated angiogenesis." (PMID 35707353, 2022). "Earlier study demonstrated that STC1 plays a critical role in tumor progression." (PMID 35392966, 2022). "In vivo tumor studies showed that KO of STC1 led to a drastically reduced tumor growth rate, significantly downregulated CSC markers (CD44 and CD166) on the surface of tumor cells, and reduced CD44+/CD166+ CSC-like cell populations within the general A549 tumor cell population." (PMID 36499099, 2022). "It has been shown that STC1 played a crucial role in promoting tumor metastasis, invasion, tumor cell proliferation, and antiapoptosis via participating in multiple signal pathways associated with cancer, including JNK/c-Jun NF-κB, cyclin E/CDK-2, and ERK1/2 signal pathways." (PMID 35273656, 2022). "Although STC1 has been reported to regulate multiple processes during tumour development and progression, the different expression pattern of STC1 and STC2 indicates they may have different roles under physiological or pathological conditions." (PMID 35501821, 2022). "However, many studies on the relationship between STC1 and tumor development have reported contradictory conclusions." (PMID 34722511, 2021). "Other examples of metastasis-promoting CAF populations include IL-11 secreting CAFs, which could activate apoptosis-suppressing programs in metastatic tumor cells, and stanniocalcin-1 (STC1) expressing CAFs." (PMID 33430285, 2021). "STC1 and STC2 in various tumor tissues have significantly higher or lower expression levels than those in the corresponding adjacent normal tissues, suggesting that STC may be correlated to the occurrence and development of tumors." (PMID 37287492, 2021). "A recent paper reported that tumor STC1 inhibits APC phagocytosis and contributes to tumor immune evasion and immunotherapy resistance, indicating a role for STC1 in the immune response, which provides a possible reason to explain why STC1 functions differently in vivo and in vitro." (PMID 34722511, 2021). "However, some tumour cells overexpress stanniocalcin 1 (STC1), which obstructs calreticulin exposure on the cell surface, reducing phagocytosis of the cancer cells." (PMID 34177884, 2021). "Our results suggest that enhancing the expression of STC-1 might be a good strategy to inhibit tumor proliferation and invasion, possibly having therapeutic implications in EC." (PMID 34650342, 2021). "Additionally, STC1 inhibits macrophage infiltration, further hindering an immune response against the tumor." (PMID 34867818, 2021).